APOE (apolipoprotein E)
Diseases named in the same sentence as APOE in open-access papers (continued):
Sharing a sentence is not in itself a finding about the gene and the disease.
infection (continued). "At this time post-infection, both signals were present in the same area of the cell, but the ApoE signal appeared to be much stronger than the Zika E protein signal." (PMID 35902969, 2022). "Employing cell culture systems of HBV production and infection, we have recently found that human apolipoprotein E (apoE) is enriched on the HBV envelope and is important for efficient HBV infection and production." (PMID 34293069, 2021). "At 2, 12, 24, and 48 h after infection, substantial levels of bacteria were present in the hearts of ApoE−/− mice after grinding mice-heart tissue, and reached a peak at 24 h." (PMID 33488579, 2020). "We collected the cells 1, 3, 7, and 14 days post-infection (d.p.i.)and analyzed them for viral DNA and RNA, ApoE, Aβ, tau, and phospho-tau (Threonine 181) by real-time immunofluorescence and cytokines by immunoenzymatic assay." (PMID 31831060, 2019). "gingivalis-mono-infection model are the inability to monitor insoluble Aβ due to the total apolipoprotein gene knockout because apolipoprotein E is one of the three essential proteins required for amyloid fibril formation." (PMID 30728914, 2019). "Human, mouse, and the triply humanized/murinized CypA constructs were then transduced into the Clone 8 + ApoE cells and the replication assessed once more by luminometry following Jc1-Gluc infection." (PMID 31074414, 2019). "Compared to mock-infected cells at day 1 post-infection, C. burnetii infection upregulated the expression of genes acat-1, acat-2, fabp-4 and apoE by more than 1.2 fold." (PMID 29390006, 2018). "During infection, for example, apoE can multi-task and simultaneously neutralize LPS and modulate lipoprotein trafficking." (PMID 29807532, 2018). "The correlation between modulation of this transcript and infection was confirmed in our ApoE−/− model." (PMID 30483256, 2018). "Removal of HSPGs abrogated the enhancement of infection by ApoE, indicating that incorporated ApoE mediated the binding to cell surface proteoglycans." (PMID 29977246, 2018). "Previous studies demonstrated the presence of Cpn in the aorta of repeatedly infected ApoE−/− mice by isolating the bacterium early two weeks after infection." (PMID 29770337, 2018). "Although co-expression of miR-122 and ApoE is required for the production of infectious particles in 293T-CLDN1 cells upon infection with HCV, expression of ApoE alone permits particle formation in cells infected with HCV122KO." (PMID 28494029, 2017). "Infection of hepatocytes Hepa 1–6 with Plasmodium berghei indicated that apoE 141–149 inactivated the sporozoites by lysis, while substitution Leu → Trp in the tandem peptide blocked the microorganisms adherence by decreasing HSPGs availability." (PMID 28660014, 2017). "Recent work has demonstrated how ApoE is indispensable for the release of core protein from infected cells for infection spread." (PMID 28750044, 2017). "Considering the role of apoE in various infections, antimicrobial peptides derived from apoE with therapeutic potential were synthesized." (PMID 28660014, 2017). "The ApoE−/− mice had a median survival time of 18 days post-infection, compared to only 9 days post-infection for the WT mice." (PMID 27647324, 2016). "On the other hand, genes linked to cell proliferation and apoptosis (e.g., BCL6, APOE, PDCD4, and RARES2) emerged as the top inhibited master molecules due to infection." (PMID 26865111, 2016). "The expression of miR-122 enhances the replication efficiency, SRBI is essential for infection, and ApoE is indispensable for the production of infectious HCV." (PMID 27302754, 2016). "In particular, the spleen, which is the principal site for the clearance of parasitized RBCs19, 20, was approximately four times larger in the ApoE−/− mice by the end of the infection." (PMID 27647324, 2016).
infection (continued). "The weight of the spleen and liver in the ApoE−/− mice was similar to the WT mice at the onset of symptoms, and significantly increased throughout the duration infection, likely due to the infiltration of parasitized RBCs and the deposition of hemozoin." (PMID 27647324, 2016). "The median survival time was 9 days post-infection for the WT mice and 18 days post-infection for the ApoE−/− mice." (PMID 27647324, 2016). "The wild-type (WT) mice succumbed to the disease within 7 to 11 days post-infection, whereas the ApoE−/− mice were significantly protected, and survived into the fourth week of infection." (PMID 27647324, 2016). "Nine weeks following the last infection with P. gingivalis, C. pneumoniae, or 9 weeks of feeding a Western diet, ApoE-/- mice were sacrificed in order to understand the changes in platelet transcripts before the formation of overt plaques." (PMID 26148065, 2015). "Since these results indicate that apoE mediates infection through basic residues contained in the HSPG-BD, we generated an apoE derived peptide (apoE-dp) consisting of a repeated sequence of the HSPG-BD." (PMID 24751902, 2014). "On the other hand, IL-17 levels were lower in APOE knockout mice after infection and under-nutrition as compared with the APOE knockout uninfected controls and with undernourished infected wild-types." (PMID 24586873, 2014). "Infection of 3T3 cells with prions resulted in reduction of cholesterol efflux to apoA-I, apoE discs, and HDL similar to the effects seen in prion-infected neuronal cells." (PMID 24280226, 2014). "In mouse models, APOE modulates infection by HSV-1, Chlamydophila, Klebsiella pneumoniae, Listeria monocytogenes and Leishmania." (PMID 24656052, 2014). "After one week post-infection, only one (1 out of 14, 7.4%) experimentally infected –APOE 4/4 TR mouse showed C. parvum shedding in stool." (PMID 24586873, 2014). "P. gingivalis successfully colonized the hyperlipidemic mice upon oral infection for 24 weeks and the high IgG titer seen in infected ApoE−/− mice demonstrated a specific host immune response against P. gingivalis." (PMID 25354050, 2014). "This raises a central question – how do APOE and cholesterol metabolism relate, at a molecular level, to infection and immunity?" (PMID 24656052, 2014). "From day 3 after infection onward, the APOE 4/4 TR mice showed an accelerated pace of oocyst reduction." (PMID 24586873, 2014). "Apolipoprotein E (ApoE) is persistently up-regulated in brain tissues at 14 and 21 days after infection with Toxoplasma cysts." (PMID 23587304, 2013). "A similar dose-dependent inhibition of infection was observed for WT and mutant viruses when HCVcc particles were pre-incubated with the anti-ApoE antibodies." (PMID 23300734, 2012). "Resistance to infection (Klebsiella pneumoniae) or endotoxaemia is also decreased in APOE knockout mice." (PMID 22254144, 2011). "Infection of apoE knockout (KO) mice with Listeria monocytogenes or Klebsiella pneumoniae leads to an increased susceptibility to death as well as increased serum levels of TNF-α as compared with wild-type (WT) mice." (PMID 21772670, 2011). "One of the most studied such connections to date is the influence of the APOE gene on the outcome of infection." (PMID 20298574, 2010). "Whereas little differences were apparent on day 1 of infection, the outgrowth of Salmonella on day 3 and 7 after the infection was 100 to 1000-fold less in the liver and spleen of ApoE−/− mice compared to that in ApoE+/+ control animals." (PMID 19156198, 2009). "Similar as in multiple infection cycles, isoform-dependent higher virus titers were also seen at middle time points (12 and 18 hpi) for ApoE groups as compared to the diluent group during virus single infection cycle, with more viruses detected in the ApoE 3 or 4 group than in the ApoE 2 one." (PMID 40295730, 2025).
infection (continued). "Findings from ApoE−/− transgenic mouse models of AD demonstrated that the oral pathogen P. gingivalis can invade the brains of these mice, with the incidence of invasion increasing with the duration of infection." (PMID 39858858, 2025). "ApoE COG 133 has demonstrated protective activity in infection and inflammation models." (PMID 41416135, 2025). "could show that experimental infection with SARS‐CoV‐2 of mice carrying the different human APOE isoforms led to increased lung pathology in carriers of APOE2 and APOE4." (PMID 41253293, 2025). "In contrast, hepatotropic virus hepatitis B (HBV) and hepatitis C (HCV) viruses require ApoE for efficient infection and virus production, and ApoE has also been co-purified together with HBV and HCV particles, suggesting incorporation of the protein into virus particles." (PMID 40295730, 2025). "Another investigation within a sizable rural Ghanaian population suggested that APOE ε4 might confer protection against infection and support fertility, particularly among women exposed to elevated pathogen levels." (PMID 39880097, 2025). "This made us investigate the potential roles of ApoE at different infection steps individually." (PMID 40295730, 2025). "Interestingly, ApoE mRNA levels were modestly increased in MHV68-infected MEFs by 24 hours post-infection, a time point that corresponds to the completion of a single MHV68 replication cycle in MEFs (16–24 hours at MOI = 1)." (PMID 40439406, 2025). "Additionally, we identified 10 genomic regions associated with breakthrough infection (SLC6A20, ST6GAL1, MUC16, FUT6, MXI1, MUC4, HMGN2P18-KRTCAP2, NFKBIZ and APOC1), and one with breakthrough severity (APOE)." (PMID 39384777, 2024). "In general, the resistance of ApoE−/− mice injected with agomir-miR-19a/b to BJ05/H1N1 infection was stronger than that of ApoE−/−+agomir-NC-treated mice, indicating that miR-19a/b may hamper the replication of influenza virus." (PMID 38435118, 2024). "We next tested if the ApoE neutralizing antibody could block the infection by the SARS‐CoV‐2 Delta strain." (PMID 37822714, 2023). "Male ApoE-/- mice aged 11-12 weeks fed a Western diet for 8 weeks prior to infection." (PMID 37033482, 2023). "APOE-ε4 carriers may be better able to clear infections in both humans and experimental rodent models." (PMID 37556539, 2023). "Our results showed that the concentration of ApoE protein in the supernatant of Mlep-infected macrophages was significantly higher than that of uninfected macrophages, especially at 48 h after infection, indicating that Mlep infection can induce macrophages to upregulate the expression of ApoE." (PMID 35013182, 2022). "Our observation is in good agreement with previously published in vivo studies on APOE-deficient mice, which show increased susceptibility to infection caused by Gram-negative bacteria or fungi." (PMID 35740451, 2022). "All the RNA transcripts obtained from the different viral constructs (TBSV-WT, -RGD, -RiGiD, -ApoE, -CooP, -tLyp1) were used to infect N. benthamiana plants and demonstrated the ability to induce on leaves the onset of typical infection symptoms (chlorotic vein clearing)." (PMID 34638864, 2021). "Further proof of concept studies in which, P. gingivalis was inoculated into the mouths of apolipoprotein E knock-out (APOE−/−) mice demonstrated P. gingivalis bacterial DNA and LPS had entered the brains of APOE−/− mice, where the infection caused a significant increase in oxidative stress." (PMID 33289908, 2021). "APOE, lipids, and immune function may interact differently in contemporary obesogenic post-industrial contexts compared to environments where infections are prevalent." (PMID 34586066, 2021). "For this, we fed male and female ApoE-/- HFD for 10 days before infection." (PMID 33417618, 2021). "However, the current data cannot provide evidence for either of these potentials, and further research is needed to disentangle the roles of APOE and lipids in infection." (PMID 34586066, 2021).
infection (continued). "iPathway analysis (Advaita) of the transcriptome of IL-4 injected HFD ApoE-/- mice suggested a distinct transcriptional landscape from what is induced by S. mansoni infection with infection modulating more genes in metabolic pathways of BMDM than IL-4c injection." (PMID 33417618, 2021). "Moreover, the different affinities of the various ApoE isoforms for cell surface receptors can affect host susceptibility to HCV infection and the ability to clear the virus after infection." (PMID 31027190, 2019). "The observed early increase in ApoE transcript expression may enhance internalization of Cpn EB’s during infection." (PMID 30786875, 2019). "Infection one or two times did not cause increase in triglyceride level, but the third Cpn inoculation resulted in a significant elevation (P = 0.001) in ApoE−/− mice." (PMID 29770337, 2018). "Immunofluorescence staining revealed a significant 91% reduction of TrkB expression in the aorta of the ApoE−/− mice infected with AAV9-shTrkB compared with the control mice with AAV9-Control infection, suggesting that the levels of TrkB in the aortic endothelial layer was efficiently knocked down." (PMID 26431274, 2015). "Therefore, we examined the effects of exogenous expression of the apolipoproteins highly expressed in the liver tissues on the infection of HCV in the stable ApoE-knockdown Huh7 cells." (PMID 25502789, 2014). "In addition, undernourished infected APOE knockout mice showed significant weight impairments after the 4th day of C. parvum challenge and showed poor growth catch-up after infection." (PMID 24586873, 2014). "Furthermore, APOE4/4 TR showed better villus height as compared to APOE 3/3 TR and APOE knockout mice following infection and under nutrition (p<0.05)." (PMID 24586873, 2014). "Not only intracellular but also extracellular infection titers were impaired in BE-KO1 cells compared with those in parental and ApoE-res cells, suggesting that intracellular particle formation is impaired by deficiencies in the expression of ApoB and ApoE." (PMID 25502789, 2014). "However, the pattern of cytokine expression after 6 weeks of infection shows a strong tendency to be higher in ApoE KO infected mice compared to the ApoE control and the C57BL/6 infected groups." (PMID 23710353, 2013). "These seemingly discordant findings led us to hypothesize that apoE regulates the host response to severe infection via its effects on NKT cell activation and the resultant cytokine secretion." (PMID 20953368, 2010). "We have shown that the influence of APOE on infection may be mediated through direct anti-infective activity of the cationic receptor-binding region of apolipoprotein E (apoE141-149)." (PMID 20298574, 2010). "The exact mechanism by which APOE ε4 may offer protection against infection remains unclear." (PMID 39880097, 2025). "While our results clearly conclude a proviral effect of ApoE on HSV1 infection and can deduce interesting insights on the importance of ApoE and how it shapes infection, our model system lacks the complexity of a true biological system that could possibly mask or alter the resulting effects." (PMID 40295730, 2025). "This interaction may, therefore, occur early in Zika E protein synthesis in the ER lumen, as indicated by the partial colocalization observed 6 h post-infection, with ApoE translocated with Zika E protein to the ER cisternae in which viral morphogenesis occurs." (PMID 35902969, 2022).
infection (continued). "To elucidate whether infection imprints macrophages with an altered metabolic phenotype we infected (and mock infected controls) atherogenesis-prone male ApoE-/-mice on HFD, and sacrificed them at 10-weeks post-infection (chronic infection) to harvest bone marrow cells." (PMID 33417618, 2021). "Thus, apolipoprotein E precursor was down-expressed in response to the experimental infection of pigs with T. britovi, and possible mechanisms of the infection-induced apoE serum expression changes are widely discussed in the previous section of this manuscript." (PMID 31940868, 2020). "It is now well-established that infection with S. mansoni alters host lipid metabolism globally by reducing total cholesterol, low-density lipoprotein (LDL) and triglycerides in the plasma of humans and apolipoprotein E (apoE)-deficient or high-fat diet-fed mice." (PMID 31681260, 2019). "Additional factors that can influence viral entry include apolipoprotein E (ApoE), which is incorporated on infectious HCV virions, and can function as an exchangeable apolipoprotein between secreted ApoE-associated lipoproteins and the HCV lipoviroparticle (LVP) to enhanced HCV infection." (PMID 30486350, 2018). "Infection with gram-negative bacteria such as Porphyromonas gingivalis leads to accelerated development of atherosclerotic lesions in mice after a high-cholesterol diet, and administration of LPS to ApoE-deficient mice results in aggravation of inflammation." (PMID 29236764, 2017). "Our previous studies have demonstrated that apoE is enriched in the envelopes of hepatitis B virus (HBV) and hepatitis C virus (HCV)and promotes their infection and morphogenesis in vitro." (PMID 42267825, 2026). "It should be noted that, in contrast to the studies in 3T3-L1 cultures, where APOE4 and APOE4mut1 were expressed by the infected cells, the in vivo results of AdAPOE4 and AdPOE4mut1 infection on BAT and WAT are due to circulating hepatically expressed APOE." (PMID 41354325, 2025). "Specifically, the potential protective effects of APOE ε4 against infection and support for fertility could have played a role in its selection in preindustrial populations characterized by a higher burden of infections and increased vulnerability to early mortality from childhood infections." (PMID 39880097, 2025). "Considering the similar infection starts and plateaus, these results suggest that one or multiple steps of the HSV1 lifecycle are promoted by ApoE, resulting in more released (cell-free) viral particles." (PMID 40295730, 2025). "In contrast to APOE, DCBLD1 was significantly downregulated in acute death cases compared to both normal and long infection cases during SARS-CoV-2 infection." (PMID 38752789, 2024). "TILT-322 infection of ovarian ascites samples led to downregulation of 14 differentially expressed genes (SLC26A4-AS1, APOE, TREM2, CD36, AC145676.1, VENTX, FP671120.4, AC007663.4, AC112220.2, C1QC, TEPP, AC027796.4, AC016026.1, and C1QA) in ascites samples." (PMID 38910324, 2024). "Here, we found that Apolipoprotein E (ApoE), a lipid binding protein, is hijacked by SARS‐CoV‐2 for infection." (PMID 37822714, 2023). "Compared to APOE E3 mice, APOE2 and APOE4 mice exhibited increased viral loads as well as suppressed adaptive immune responses early after infection." (PMID 36845144, 2023). "AVPs that resemble the cellular protein apolipoprotein E (ApoE) can break up the glycan-dependent interaction or attachment of HCV, hindering entry and infection of target host cells (hepatocytes)." (PMID 35565968, 2022). "Since cellular SARS-CoV-2 entry is initiated by docking of the viral Spike protein to the ACE2 receptor, we tested if APOE can interact with ACE2 and thereby modulate ACE2/Spike protein interactions during viral entry and infection." (PMID 35915083, 2022).